AR (androgen receptor)
Diseases named in the same sentence as AR in open-access papers (continued):
Sharing a sentence is not in itself a finding about the gene and the disease.
prostate carcinoma (continued). "Our results demonstrate that androgen-stimulated PAK6 activation is mediated through a direct interaction between AR and PAK6 and PAK6 activation promotes prostate cancer cells motility and invasion." (PMID 24130878, 2013). "We have previously demonstrated that β1 integrins regulate anchorage-independent growth of prostate cancer (PrCa) cells by regulating IGF-IR expression and androgen receptor-mediated transcriptional functions." (PMID 24130778, 2013). "In the castration-resistant prostate cancer cell line CWR-R1, endogenous expression of Sox2 was repressed by AR signaling, and AR chromatin-IP shows that AR binds the enhancer element within the Sox2 promoter." (PMID 23326489, 2013). "The very signaling pathways now recognized as being cholesterol-dependent: AR, TGFβ, EGF, MAPK/ERK, AP-1, and AKT, are well characterized as prostate cancer relevant." (PMID 23919967, 2013). "In prostate cancer, however, when FOXA1 is lost, AR can still bind to chromatin and in fact occupies new binding sites which are coupled to changes in its' transcriptional targets." (PMID 23420418, 2013). "The transcription factors AR and Sp1 were shown to form a nuclear complex and both bound the VEGF core promoter in chromatin of hormone treated CWR22Rv1 prostate cancer cells." (PMID 23369005, 2013). "AR directly regulates CAMKK2 and is highly expressed in normal prostate with elevated expression in both AR-sensitive and CRPC models of prostate cancer." (PMID 23573093, 2013). "Taken together, these data suggest that AR signaling plays a critical role in hormone-sensitive and CRPC and remains an important target for prostate cancer therapeutics." (PMID 22509301, 2012). "Although the function of YY1 in prostate cancer is not fully known, it was reported recently that YY1 forms a complex with AR, which together binds to the ARE within the PSA promoter, stimulating gene expression." (PMID 22536409, 2012). "Activated ERK mediates activation of the androgen receptor and/or PSA secretion through the growth factor receptor tyrosine kinase, Her2/Neu (also known as erbB2) in androgen-independent prostate cancer cells." (PMID 22046506, 2012). "Taken together, our findings suggest that COUP-TF II is a novel corepressor of AR, and provide an insight into the role of COUP-TF II in prostate cancers." (PMID 23145053, 2012). "After the AR shRNAs were loaded inside the particles, the surface of the nanoparticles was then conjugated with the A10 anti-PSMA aptamer for prostate cancer cell-specific targeting." (PMID 23130020, 2012). "In prostate cancer, accumulating evidence has indicated that EGFR/ERBB2 signals induce AR transactivation in an androgen-dependent and -independent manner." (PMID 22922989, 2012). "Activated ACK1 has been detected in advanced human prostate cancers where it has been shown to phosphorylate three cancer relevant substrates in prostate cancer cell lines: WWOX, AKT, and androgen receptor." (PMID 22615583, 2012). "In the present study, we explored a putative role of COUP-TF II in prostate cancers by investigating its effect on cell proliferation and a cross-talk between COUP-TF II and AR." (PMID 23145053, 2012). "Others also described negative regulation of AR expression and activity by EGFR signaling in prostate cancer." (PMID 22922989, 2012). "Our findings suggest cholesterol-targeting therapy may inhibit the growth of aggressive prostate cancers via attenuation of intracrine steroidogenesis and, further, that this approach may synergize with therapies directly targeting androgen synthesis and the AR." (PMID 22279565, 2012). "Prostate cancer cell proliferation and hypoxia-induced angiogenesis are also regulated by the SUMO pathway, through an AR-independent mechanism." (PMID 24970135, 2012). "The ability of COUP-TF II to repress AR function and inhibit the growth of prostate cancer cells makes COUP-TF II a new candidate as a therapeutic target for prostate cancers." (PMID 23145053, 2012).
prostate carcinoma (continued). "CT (5 and 25 mg/kg, every other day by i.p. for four weeks) decreased tumor weight and the mRNA levels of AR-dependent transactional genes such as PSA and TMPRSS2 in 22Rv1 prostate cancer xenografts, all in dose-dependent manners." (PMID 23202971, 2012). "AR directly regulates CAMKK2 by binding to its promoter and is highly expressed in normal prostate with elevated expression in both AR-sensitive and CRPC models of prostate cancer." (PMID 22548055, 2012). "Due to the important role that AR plays in primary prostate cancer and CRPC, AR remains a relevant therapeutic target." (PMID 22509301, 2012). "In vivo, TIIA (oral daily, 25 mg/kg, four weeks) decreased AR and PSA levels in LNCaP prostate cancer xenografts, accompanied by a reduction of tumor burden." (PMID 23202971, 2012). "We also identified that salinomycin reduced the expression of prostate cancer oncogenes, MYC, AR and ERG, which are known to have antioxidative properties." (PMID 22215106, 2012). "Several regulatory pathways, such as the androgen receptor (AR) signaling pathway and Akt/protein kinase B (PKB) signaling pathway play a key role in the regulation of apoptosis and proliferation in prostate cancer cells 6–10." (PMID 23029264, 2012). "Western blot analysis identified high levels of expression of AR in ARIBE-1 and ARIBE-2, which was higher than the expression in MDA-MB-453 cells, but comparable with levels in the AR-positive prostate cancer cell line LNCaP." (PMID 22321971, 2012). "Growth factor stimulation has been reported to render AR-responsive promoters hypersensitive to androgen, and forced over expression of HER2/neu in androgen-dependent prostate cancer cells has been shown to drive castration-resistant growth." (PMID 22761715, 2012). "For instance, ERβ, localized in prostate epithelial cells together with AR and DAX1, is pro-apoptotic, anti-proliferative and anti-inflammatory and impedes prostate cancer EMT." (PMID 22849360, 2012). "As reported here, HE3235 diminished AR and ERα expression in the rat MNU model and was previously reported to decrease AR expression in a hormone-independent prostate cancer xenograft model." (PMID 22332014, 2011). "Recent reports show Pax6 to be a repressor of AR activity, and the PAX6 gene to be hypermethylated in prostate cancer cells." (PMID 21935435, 2011). "LNCaP human prostate cancer cell line recapitulates important features of prostate cancer including expression of both prostate-specific antigen (PSA) and AR as well as sensitivity to androgen." (PMID 21909421, 2011). "Here, we assessed the role of ZMIZ1, an AR co-activator, in regulating the activity of the AR with different lengths of polyQ tracts as ARQ9, ARQ24, and ARQ35 in prostate cancer cells." (PMID 21949845, 2011). "Overall, while further studies are needed to resolve the role of FUS in prostate cancer disease progression, this study revealed that: 1) FUS interacts with AR; and 2) FUS enhances the transcriptional activity of AR." (PMID 21909421, 2011). "Similar to previously reported, we also confirmed the AR regulation roles in the differentiation of tumor cells by specifically knocking out epithelial AR from the transgenic adenocarcinoma of the mouse prostate (TRAMP) that could spontaneously developed prostate cancer." (PMID 21754978, 2011). "In summary, Pax6, SPBP and AR are coexpressed in the B3 lens epithelial and PC3 prostate cancer cell lines." (PMID 21935435, 2011). "Since prostate cancer cells require androgens for their survival and growth, the golden standard for the treatment of evasive prostate tumors is androgen ablation through chemical or surgical castration, which may be combined with the administration of androgen receptor (AR) antagonists." (PMID 21829708, 2011). "In prostate cancer cell line, 17-AAG induced G1 arrest by degradating HER2, Akt, and androgen receptor." (PMID 21283735, 2011).
prostate carcinoma (continued). "In prostate cancer, FKBP51 is part of a superchaperone complex that includes androgen receptor (AR) and androgen." (PMID 22087835, 2011). "Therefore, it would be interesting to characterize the expression of ZMIZ1 and different length polyQ AR in patient samples of prostate cancer, AIS, and other human disorders that may be closely related to either loss or gain-of-function mutations in the AR gene." (PMID 21949845, 2011). "Several known cancer pathways were observed in human prostate cancer, and the study revealed that nearly all metastases contained changes in P13K, RAS/RAF, and androgen receptor pathways." (PMID 21949592, 2011). "PCSD1 xenograft tumors were characterized as PSA+, AR+, K5-, K14-, K8+, K18+, AMACR+, NKX3.1+, and TMPRSS2:ERG- human prostate cancer." (PMID 22035283, 2011). "Functionally, WT1 has been shown to regulate genes important in prostate cancer including VEGF, Bcl2, AR, and IGF1R." (PMID 20426842, 2010). "In another subtype of prostate cancer cells (e.g., PC-82 and CWR22), AR is expressed and has acquired a gain-of-function such that it no longer inhibits but now stimulates proliferation when activated by physiological levels of androgen." (PMID 20628607, 2010). "As AR is known to play a major role in the DHT-mediated prostate cancer growth, possible effects of BFA were examined on biological activity and cellular expression of AR." (PMID 20102617, 2010). "The interaction between androgen receptor and EGFR in the caveolae of prostate cancer cells has been recently reported." (PMID 21124760, 2010). "As a coactivator of AR, FHL2 in turn robustly stimulates the AR activity that is critical for prostate cancer progression." (PMID 20442768, 2010). "Since AR is a major factor playing an essential role in the androgen-dependent prostate cancer growth, we then examined the effects of BFA on (biological) activity and expression of AR." (PMID 20102617, 2010). "AR is an important downstream target of MAPK/Erk pathways, and inhibition of Erk1/2 activity will lead to a decreased expression of AR in prostate cancer cells." (PMID 19956729, 2009). "Taken together, the up-regulation of the AR, IGF-1 signaling proteins, and their downstream effectors (ERKs) suggest a potential mechanism for prostate cancer development in the SV-40 Tag rat model." (PMID 19171036, 2009). "Future investigation will continue to analyze AR malfunction in AIS and other clinical conditions, such as prostate cancer, hypospadias, cryptorchidism and sarcopenia." (PMID 20011049, 2009). "AR and prostate specific antigen (PSA), the utmost useful biological maker of prostate cancer, express continuously in hormone-independent prostate cancers." (PMID 19816598, 2009). "Prostate cancer cells resemble those of the luminal layer, particularly in their expression of prostate-specific antigen (PSA) and the androgen receptor (AR)." (PMID 19002168, 2008). "It would be conceivable that a new generation of the AR antagonists could not only repress the AR mediated transcription, but also effectively disrupt the interaction with other pathways that can lead to the growth and transformation of castration-refractory prostate cancer." (PMID 18218096, 2008). "In this study, we further demonstrate that treatment with high doses of PL can activate caspase 8-initiated apoptotic signalling in both AR-expressing (LNCaP) and AR-null (PC3) prostate cancer cells." (PMID 17262078, 2007). "Our recent studies using tissue microarrays and dual immunofluoresence indicate that in prostate cancer, DDC is not only a neuroendocrine (NE) marker, but is also co-expressed with AR in a subset of NE tumor cells." (PMID 17553164, 2007). "We used human androgen-dependent prostate cancer cells (LNCaP), since our primary goal was to assess the co-activation function of DDC, known to enhance AR activity through an androgen-dependent mechanism." (PMID 17553164, 2007).
prostate carcinoma (continued). "It has been previously shown through in vitro studies that cyclin D1 can influence androgen-dependent prostate cancer cell proliferation through its dual ability to modulate both CDK4 and AR activity." (PMID 17375037, 2007). "Briefly, AR-T877A–expressing prostate cancer cells (LNCaP) were initially cultured in hormone-depleted conditions (CDT), to suppress cell cycle progression and deplete endogenous AR of ligand." (PMID 18007998, 2007). "Methylation of the AR gene promoter has been reported in advanced hormone-independent prostate cancer tissue and the addition of 5-Aza-2'-deoxycytidine(5-AZA) into DU145 cells with a heavily methylated AR promoter restored AR mRNA expression." (PMID 16774685, 2006). "Depending on the status of AR, suppression of either pathway by HOXB13 seems to inhibit the growth of prostate cancer cells." (PMID 15928669, 2005). "This is the first study to our knowledge that has correlated AR gene amplification, AR protein expression and PSA protein expression in matched hormone-sensitive and hormone-resistant prostate cancer." (PMID 12888829, 2003). "In prostate cancer cell lines, we found variable levels of the RAC 3 protein with highest expression seen in AR-positive LNCaP cells, moderate expression in AR-negative PC 3 cells and low-level expression in AR-negative DU 145 cells." (PMID 11747336, 2001). "As co-activators are also known to enhance androgen receptor (AR) activity, we investigated the role of RAC 3 in the context of prostate cancer." (PMID 11747336, 2001). "Accurate measurement of androgen receptor pathway inhibitors (ARPIs) and their active metabolites is essential for pharmacokinetic studies and therapeutic drug monitoring (TDM) in patients with prostate cancer (PC)." (PMID 41977206, 2026). "In prostate cancer organoids, CDK12 inactivation enhances androgen-receptor (AR) signaling and induces enzalutamide resistance, whereas combined inhibition of CDK12/13 (THZ-531) and AR blockade (bicalutamide, apalutamide, or enzalutamide) exerts synergistic cytotoxicity." (PMID 41491919, 2026). "Prostate cancer (PC) is one of the most common malignancies in men, and the emergence of androgen receptor-low/negative castration-resistant PC (ARL/- CRPC) following androgen receptor signaling inhibitor (ARSI) therapy remains a critical clinical challenge." (PMID 42082606, 2026). "Collaborators of the transcription factor AR have been found to modulate the AR cistrome, both in the normal prostate and at each stage of prostate cancer progression." (PMID 41602415, 2026). "Our study identified novel prostate cancer therapeutic targets independent of the AR signaling pathway and established a research paradigm for developing anti-tumor agents through integrative cancer bioinformatics and network pharmacology analysis." (PMID 41492471, 2026). "AR-targeted therapy restores IKKε expression and enables IFN signaling in prostate cancer cells." (PMID 41542764, 2026). "In contrast, modulation of HDAC11 does not alter AR splicing in prostate cancer cells, indicating cell type specific regulation." (PMID 42124652, 2026). "NEPC, characterized by a diminished AR signaling pathway, is a lethal stage of prostate cancer that does not respond to androgen deprivation therapies, the primary treatment strategy for both ADPC and CRPC." (PMID 41492471, 2026). "In the genitourinary system, dihydrotestosterone promotes the expression of FAM64A by binding of the androgen receptor to the FAM64A promoter, thereby enhancing the proliferation, migration, and cell cycle progression of androgen-dependent prostate cancer cell lines." (PMID 41682010, 2026). "Preclinical targeting of this axis suggested a potential therapeutic strategy, as suppressed tumor growth in prostate cancer xenograft was observed following LF knockdown coupled with ferroptosis induction (via IKE) and androgen receptor inhibition (via enzalutamide)." (PMID 41945871, 2026).
prostate carcinoma (continued). "Similarly, PAD2 expression is regulated by androgens in prostate cancer cells, and interestingly, PAD2 regulates the stability and nuclear import of AR protein and AR target gene expression." (PMID 41226560, 2025). "Notably, the androgen receptor-independent transactivation of KHDC4 and TRAF2 by E2F4 was demonstrated using multiple prostate cancer cell lines and further validated through clinically relevant transcriptome datasets." (PMID 40560737, 2025). "Therapeutically, co- administration of the AR inhibitor enzalutamide and the ferroptosis inducer RSL3 significantly suppressed tumor growth, offering a promising strategy for castration-resistant prostate cancer." (PMID 40082405, 2025). "Furthermore, our results suggest that PROX1 targeting through HDACis is a rational approach to treat tumors across the prostate cancer lineage plasticity continuum that have upregulated PROX1 and lost AR reliance." (PMID 40454483, 2025). "Phase III trials of androgen receptor pathway inhibitors for nonmetastatic castration‐resistant prostate cancer." (PMID 40572035, 2025). "In several cell lines frequently utilized in investigations on prostate cancer, ARV‐110 at 10 nM could destroy 95% to 98% of AR within 24 h." (PMID 39898116, 2025). "Enzalutamide is a second-generation potent antagonist of the androgen receptor utilized for metastatic and non-metastatic prostate cancer." (PMID 40417209, 2025). "Therefore, the mainstay therapy for prostate cancer tends to be Androgen deprivation therapy (ADT) through antiandrogens and AR inhibitors such as enzalutamide." (PMID 40699691, 2025). "To investigate whether the growth inhibitory effects of NXP800 were exclusively through AR signaling abrogation, we interrogated AR-positive (VCaP, LNCaP, LNCaP95, and 22Rv1) and AR-negative (PC3 and DU145) prostate cancer cell lines." (PMID 39787247, 2025). "The androgen-responsiveness of the p21 promoter in prostate cancer cells is also due to AR/Sp1 interaction, whereas the induction of the AR coactivator, nuclear receptor interaction protein (NRIP), involves AR-Sp, which includes an androgen response element (ARE) and GC-rich sites." (PMID 39858066, 2025). "This may provide an explanation to the discrepancies seen with NKX3.1’s role in early-stages of prostate cancer, given that factors like SOX2 are AR-repressed and upregulated after androgen targeted therapy and promote therapeutic resistance." (PMID 39858088, 2025). "It inhibited AR-positive prostate cancer cell proliferation (LNCaP and CWR22Rv1) at 0.5 μM, while exerting minimal effects on AR-negative PC-3 cells and non-malignant RWPE-1 prostate epithelial cells." (PMID 41020902, 2025). "The connection between AR-regulated TMPRSS2 expression and SARS-CoV-2 entry has prompted investigations into whether ADT might confer protection against COVID-19 severity in prostate cancer patients, though results have been inconsistent." (PMID 41150771, 2025). "Cluster 1 included signatures associated with immune response, WNT and TGF beta signaling, epithelial‐mesenchymal transition, prostate cancer basal differentiation, and AR low/double negative prostate cancer subtypes." (PMID 39985777, 2025). "We supplemented a panel of AR-positive and negative prostate cancer cell lines with these CMs and evaluated their cell number after 7 days of continuous exposure." (PMID 40268923, 2025). "Importantly, ENZ treatment enhanced the sensitivity of prostate cancer cells to RSL3, a selective ferroptosis inducer, indicating that AR inhibition potentiates ferroptosis." (PMID 40082405, 2025). "The combination of apalutamide, a nonsteroidal androgen receptor inhibitor, with androgen deprivation therapy enhances survival in patients with metastatic castration-sensitive prostate cancer." (PMID 41024304, 2025).